FABP5 (fatty acid binding protein 5)
Diseases named in the same sentence as FABP5 in open-access papers (continued):
Sharing a sentence is not in itself a finding about the gene and the disease.
infection (11 papers, 2013 to 2025). The state of being infected such as from the introduction of a foreign agent such as serum, vaccine, antigenic substance or organism. "Thus we hypothesized that CS-induced FABP5 down regulation in airway epithelial cells increases inflammation and infection susceptibility by decreasing PPAR-γ activity." (PMID 23349676, 2013). "A recent study investigated the response of lung epithelial cells to infection by the influenza virus, thereby adding more evidence on the link between FABP5 and the immune system." (PMID 35445019, 2022). "Here, we investigated the functional cooperation between FABP5 and PPARγ in a monocytic-derived cell line and in human PBMCs in response to CS exposure and infection." (PMID 30877402, 2019). "Taken together, these results suggest that FABP5 is critical to prevent CS and infection-induced pulmonary inflammation." (PMID 30877402, 2019). "The combination of both CS exposure and P. aeruginosa infection resulted in similar FABP5 mRNA levels as observed for the infection alone in the lung homogenates of WT mice." (PMID 30877402, 2019). "Infection of C57BL/6J background mice with H1N1 influenza A virus from which the FABP5 (FABP5−/−) gene had been deleted revealed that FABP5 deficiency augments excessive oxidative damage, lipid peroxidation, and inflammation." (PMID 30871179, 2019). "Using wildtype (WT) and FABP5−/− mice, we examined the effects of FABP5 on CS and infection-induced inflammatory responses." (PMID 30877402, 2019). "The combination of CS exposure and bacterial infection led to increased inflammation compared to infection alone, with a significant worsening of lung histopathology score in FABP5−/− mice compared to WT mice." (PMID 30877402, 2019). "Understanding how FABP5 expression is regulated during infection will open up novel possibilities to enhance COPD patients’ innate immune defense mechanisms against repeated episodes of infections." (PMID 28542209, 2017). "The airway epithelium constitutes the first line of host defense against infection and our previous study indicated that Fatty Acid Binding Protein 5 (FABP5) is down regulated in airway epithelial cells of smokers with COPD as compared to smokers without COPD." (PMID 23349676, 2013). "Interestingly, the expression of FABP5 in wild-type lung tissue was decreased after infection with the influenza A virus, which is in conjunction with a decrease in the anti-inflammatory molecule PPAR-γ activity." (PMID 35445019, 2022). "Understanding the role of FABP5 during infections in the presence of CS may open up new therapies for the treatment and/or prediction of recurrent exacerbations of COPD." (PMID 30877402, 2019). "Similarly to what we saw in airway epithelial cells, infection increased FABP5 expression while CS decreased FABP5 expression in mouse lung tissues." (PMID 30877402, 2019). "In summary, our study shows that FABP5 promotes the resolution of CS and infection-induced inflammation and that it may do so through PPARγ activation." (PMID 30877402, 2019). "Taken together, these results indicate that the human lung epithelial BEAS-2B cells behave similarly to primary human cells regarding FABP5 gene expression, and therefore are an adequate model to study the regulation of FABP5 expression by cigarette smoke and/or infection." (PMID 28542209, 2017). "Using whole-body CS exposure in WT and FABP5−/− mice to test the hypothesis that FABP5 is required for dampening CS- and infection-induced inflammation, we show that FABP5−/− animals mount an exaggerated inflammatory response to P. aeruginosa infection following CS exposure." (PMID 30877402, 2019).
bacterial infection (7 papers, 2009 to 2025). "High FABP5 levels are linked to increased immune cell infiltration and bacterial infection response, both crucial in periodontal tissue destruction." (PMID 40808852, 2025). "In this study, we confirmed that CS inhibits bacteria-induced FABP5 expression, using P. aeruginosa, which resulted in increased airway epithelial cell susceptibility to bacterial infection and inflammation." (PMID 23349676, 2013). "In recent studies, FABP5 has been shown to play a protective role during bacterial infection of the lung by increasing PPAR-γ activity." (PMID 34876574, 2021). "Taken together these data confirm that FABP5−/− mice have increased inflammation following CS exposure and bacterial infection." (PMID 30877402, 2019). "We further showed that FABP5 exerts immunomodulatory functions in the airway epithelium against CS exposure and subsequent bacterial infection through its modulation of the nuclear receptor peroxisome proliferator-activated receptor (PPAR)-γ activity." (PMID 30877402, 2019). "To define the role of FABP5 in CS- and exacerbation-induced responses, we measured the effects of CS and bacterial infection on FABP5 expression in wild type (WT) mice exposed to 5 days of CS or filtered air." (PMID 30877402, 2019). "We have previously shown that bacterial infection and cigarette smoke exposure differentially regulate FABP5 expression, however little is known about the molecular mechanisms of FABP5 gene regulation." (PMID 28542209, 2017). "We knocked down or overexpressed FABP5 in primary NHBE cells to determine FABP5 host defense mechanisms during bacterial infection in the context of CS exposure." (PMID 23349676, 2013). "Taken together, these results confirm the protective role of FABP5 during bacterial infection in the context of CS exposure." (PMID 23349676, 2013). "Our study indicates that FABP5 exerts immunomodulatory functions in the airway epithelium against CS exposure and subsequent bacterial infection through its modulation of the nuclear receptor peroxisome proliferator-activated receptor (PPAR)-γ activity." (PMID 23349676, 2013). "In this report, we show that FABP5 is increased following bacterial infection but decreased following CS exposure of primary normal human bronchial epithelial (NHBE) cells." (PMID 23349676, 2013). "Ablation of FABP5 expression sensitized NHBE cells to CS-induced inhibition of innate immunity whereas FABP5 overexpression protected the cells from CS-induced bacterial infection worsening." (PMID 23349676, 2013). "We show that FABP-5 is up-regulated in airway epithelial culture upon bacterial infection, demonstrating its potential role in the innate immune response." (PMID 19718433, 2009). "Lastly, we showed that expression of FABP-5, the human orthologue of lbp-7, was also up-regulated by bacterial infection." (PMID 19718433, 2009). "Interestingly the human orthologue of this protein, FABP5, was up-regulated in response to bacterial infection, and was down-regulated in COPD patients as compared to healthy smokers." (PMID 30877402, 2019). "We hypothesized that cigarette smoke (CS) exposure down regulates FABP5, thus, contributing to a more sustained inflammation in response to bacterial infection." (PMID 23349676, 2013). "This study confirmed our hypothesis that CS decreases FABP5 expression in airway epithelial cells and contributes to a more sustained bacterial infection." (PMID 23349676, 2013). "Additionally, our work provides new opportunities for studying the role of FABP5 in bacterial infections under disease conditions such as COPD." (PMID 23349676, 2013). "However, our study shows that reduced FABP5 level in airway epithelial cells is detrimental against bacterial infection and, as a result, COPD exacerbations." (PMID 23349676, 2013).
bacterial infection (continued). "Interestingly the human orthologue of this protein, FABP-5, was also present in human bronchial epithelial cells, was up-regulated in response to bacterial infection, and was down-regulated in COPD patients as compared to healthy smokers." (PMID 19718433, 2009). "FABP5, a novel anti-inflammatory protein, is significantly reduced in inflammatory lung diseases including COPD, which may render the patients more susceptible to bacterial infections." (PMID 28542209, 2017). "Therefore, our experiments with the BEAS-2B lung epithelial cell line suggest that LPS-induced FABP5 up-regulation may be part of an effective innate host response aimed at protecting lung tissue against bacterial infection-induced inflammation." (PMID 28542209, 2017). "In summary, our study shows that CS modulates the expression of FABP5 in primary NHBE cells, thus contributing to their sensitivity to bacterial infection." (PMID 23349676, 2013). "The susceptibility of smokers and COPD patients to CS-dependent diseases may be related to FABP5 expression in airway epithelial cell and its modulation of PPAR-γ activity during bacterial infection." (PMID 23349676, 2013).
cardiovascular disease (7 papers, 2011 to 2025). "Fabp2 and Fabp5 have been implicated in the pathogenesis of allergic airway inflammation as well as chronic inflammation associated with cardiovascular disease." (PMID 21738667, 2011).
peripheral neuropathy (3 papers, 2024 to 2025). A disorder affecting the peripheral nervous system. "This work now shows that ART26.12, a novel and selective inhibitor of FABP5, can prevent and treat multiple preclinical models of peripheral neuropathy." (PMID 39188040, 2025). "ART26.12 is a novel fatty acid‐binding protein 5 inhibitor, which our group showed could prevent and treat persistent pain in a preclinical model of oxaliplatin‐induced peripheral neuropathy." (PMID 39188040, 2025). "In addition, it has been reported that inhibition of fatty acid-binding protein 5 (FABP5), an intracellular fatty-acid binding protein that regulates lipid signaling and metabolism, may also ameliorate peripheral neuropathy." (PMID 40917479, 2025). "We recently showed that the novel FABP5 inhibitor ART26.12 prevented and treated oxaliplatin‐induced peripheral neuropathy (OIPN) in a CB1‐dependent manner, with involvement from TRPV1, CB2 and peroxisome proliferator‐activated receptor alpha." (PMID 39188040, 2025).
digestive system tumors (2 papers, 2020 to 2025). "Our study confirms that the overexpression of FABP5 is associated with poorer clinical–pathological features and reduced overall survival in patients with digestive system tumors, as demonstrated through meta‐analysis." (PMID 40178066, 2025). "Our findings indicate that patients with digestive system tumors who exhibit overexpression of FABP5 have poorer survival outcomes." (PMID 40178066, 2025). "To address this gap, we conducted a meta‐analysis of available studies to examine the impact of FABP5 expression on the clinicopathological features and prognosis of digestive system tumors." (PMID 40178066, 2025).
inflammation (2 papers, 2019 to 2020). Aberrant reaction of the microcirculation characterized by movement of fluid and leukocytes from the blood into extravascular tissues. "To evaluate the precise role of FABP5 in allergic lung inflammation, we intranasally administrated recombinant IL-33, one of the cytokines known to cause lung inflammation through ILC2 activation, into mice and examined lung inflammation in wild-type and Fabp5−/− mice." (PMID 33024217, 2020).
digestive system cancer (1 paper, 2025). A primary or metastatic malignant neoplasm involving any part of the digestive system. "FABP5 represents a valuable molecular biomarker for the treatment of digestive system cancers and requires further investigation in the future." (PMID 40178066, 2025).
neurodegenerative disease (1 paper, 2025). A disorder of the central nervous system characterized by gradual and progressive loss of neural tissue and neurologic function. "24.2% of microglia differentially expressed genes such as Gpnmb, Spp1, and Fabp5, which are associated with neurodegenerative diseases, thus we called this population Disease-Associated35,36." (PMID 40501958, 2025).
FABP5 also shares sentences with these, for which no sentence is quoted: Hepatic steatosis (7 papers); Alzheimer disease (5); cutaneous melanoma (3); Glucose intolerance (3); multiple myeloma (3); neurologic diseases (3); Parkinson disease (3); bladder squamous cell carcinoma (2); cervical squamous cell carcinoma (2); dry eyes (2); fibrosis (2); head and neck squamous cell carcinoma (2); hyperglycaemia (2); injury (2); intrahepatic cholangiocarcinoma (2); medulloblastoma (2); myocardial infarct (2); osteoporosis (2); retinoblastoma (2); acute lymphoblastic leukemia (1); Allergy (1); amyotrophic lateral sclerosis (1); autism (1); autoimmune disorders (1); benign fibroma (1); benign papillomas (1); benign prostate tumor (1); bladder tumors (1); carotid atherosclerosis (1); cerebral infarction (1).
A further 56 diseases each share a sentence with FABP5 in 1 paper.